DDX3X (DEAD-box helicase 3 X-linked)
Diseases named in the same sentence as DDX3X in open-access papers (continued):
Sharing a sentence is not in itself a finding about the gene and the disease.
viral infection (continued). "Finally, we also discuss the role of DDX3X-mediated translation regulation during viral infections." (PMID 36393867, 2022). "However, upon exposure to invasive RNA during acute-phase virus infection, DDX3X supports cytosolic signaling events leading to IFN-I expression, redistributing to the nucleus to help drive transcription contributing to IFN-I mediated immunity and T-cell recruitment/activation." (PMID 31575075, 2019). "DDX3X inhibits virus replication through the RLR pathway, and its abnormal function leads to persistent viral infection." (PMID 40606174, 2025). "DDX3, also known as DDX3X or DBX, has been studied in various human diseases and pathological processes, including viral infection, inflammation, and cancer." (PMID 38689093, 2024). "DDX3X plays an important role as a direct regulator of ALKBH5, mediating the modulation of demethylation of m6As during viral infections." (PMID 35897696, 2022). "The DEAD-box helicase family member DDX3X (DBX, DDX3) functions in nearly all stages of RNA metabolism and participates in the progression of many diseases, including virus infection, inflammation, intellectual disabilities and cancer." (PMID 33627125, 2021). "Another example is DDX3X, a DEAD box helicase which can respond to stressors (e.g., viral infections) by switching subcellular compartments." (PMID 34879078, 2021). "Together, these results indicate that DDX3X is an important RNA helicase involved in EV71 IRES-dependent translation and that IRES translation is enhanced by viral infection, partly mediated by viral protease activity." (PMID 29971060, 2018). "It has also been reported that DDX3X is involved in cell signaling, including IFN-α and IFN-β inducing pathways upon viral infection as well as in Wnt signaling." (PMID 28030561, 2016). "It has also been reported that DDX3X is involved in cell signaling, including a role in IFN-α and IFN-β inducing pathways upon viral infection as well as in Wnt/Wg signaling." (PMID 28030561, 2016). "Our study suggests that DDX3X prevents antiviral response against endogenous dsRNAs in the steady-state cell condition (without a viral infection or synthetic dsRNA treatment)." (PMID 35874614, 2022). "As expected, viral infection resulted in strong activation of many of these genes in cells expressing wild-type, but not in cells expressing nuclear export defective, DDX3X." (PMID 31575075, 2019). "Recent studies revealed that PTEN and DDX3X were activated by invading DENV, suggesting that host might inhibit virus infection by targeting viral transcripts with host miRNAs." (PMID 29301573, 2018). "Together, all these data demonstrate that the EV71 IRES activity is significantly stimulated by viral infection and that DDX3X is important for the IRES-dependent translation but not the cap-dependent translation." (PMID 29971060, 2018). "Thus, rather than capturing snapshots of DDX3X’s function during viral invasion, it should instead be systematically explored at multiple time points during viral infection." (PMID 36110852, 2022). "DDX3X could also regulate antiviral response by stimulating the production of IFN-I and supplementing the function of RIG-I and MDA-5 in the early phase of virus infection." (PMID 33808870, 2021). "Of particular interest is DDX3X, a crucial regulator of the TBK1/IRF3 signaling leading to induction of IFN-β31,32, which may potentially modulate airway epithelial innate responses against viral infections." (PMID 29615635, 2018).
medulloblastoma (42 papers, 2012 to 2025). A malignant, invasive embryonal neoplasm arising from the cerebellum. "Further research is required to fully characterize the effect of the DDX3X medulloblastoma mutations in vivo, perhaps including the generation of Ddx3x mutant knock-in mouse lines." (PMID 39062517, 2024). "It then examines our current understanding of the oncogenic mechanism of the DDX3X mutations in medulloblastoma, including the effect of these DDX3X mutations on growth, biochemical functions, translation, and stress responses." (PMID 39062517, 2024). "The three studies above also examined the effect of the medulloblastoma-associated mutations on the biochemical activity of the DDX3X/Ded1 protein in vitro." (PMID 39062517, 2024). "An alternative treatment strategy would thus be to restore the wild-type function of mutated DDX3X in medulloblastoma patients." (PMID 39062517, 2024). "All in all, the sequencing studies identified 42 different sites in DDX3X that were mutated in medulloblastoma patients." (PMID 39062517, 2024). "The pathological mechanism of DDX3X mutations in the causation of medulloblastoma is poorly understood, but several studies have examined their role in promoting cancer progression." (PMID 39062517, 2024). "Genomic sequencing of medulloblastoma patients has shown that DDX3X, which encodes an RNA helicase involved in the process of translation initiation, is among the most commonly mutated genes in medulloblastoma." (PMID 39062517, 2024). "Taken together, these results suggest that the medulloblastoma mutations in DDX3X induce complex changes in the translatome, likely through the effects of DDX3X on 5′ UTR structure, resulting in medulloblastoma progression." (PMID 39062517, 2024). "In 2012, a series of papers were published that used next-generation sequencing techniques to focus on the genomic changes associated with pediatric medulloblastoma, and they identified DDX3X as one of the commonly recurring mutated genes in this disease." (PMID 39062517, 2024). "Its human ortholog, DDX3X, has been implicated in multiple cancers, including frequent mutations in medulloblastoma, and DDX3X mutations also cause an autism-like cognitive disorder." (PMID 36409020, 2023). "DDX3X, located in Xp11.4, encodes for an RNA helicase linked to somatic mutations in medulloblastoma." (PMID 35406420, 2022). "Knockdown of DDX3X results in a reduction in cyclin E1 causing cell cycle arrest in the G1 phase in breast, lung, colorectal and prostate cancers and in medulloblastoma." (PMID 35954483, 2022). "Multiple malignancies have a solid association with somatic DDX3X variants, like malignant melanoma and medulloblastoma." (PMID 35392274, 2022). "Consistently, DDX3X mutations that enhance the transactivation capacity of a mutant β-catenin were found in medulloblastoma." (PMID 35954483, 2022). "Mutations in DDX3X are frequent in subgroups of medulloblastoma, and expression of DDX3X mutants potentiated Wnt pathway signaling." (PMID 36376979, 2022). "This work suggests that future studies into medulloblastoma pathology should focus on this specific translation defect, while taking into account the wide spectrum of DDX3X mutations." (PMID 33460649, 2021). "We next sought to identify which cellular and molecular processes are affected by the medulloblastoma-associated mutations in DDX3X/DED1." (PMID 33460649, 2021). "Despite the high frequency of mutations in the Wnt subtype of medulloblastoma and a reported direct effect on Wnt signaling by DDX3X, only minimal effects on Wnt signaling were observed with the mutants in reporter assays." (PMID 33460649, 2021).
medulloblastoma (continued). "Medulloblastoma is the most common pediatric brain cancer, and sequencing studies identified frequent mutations in DDX3X, a DEAD-box RNA helicase primarily implicated in translation." (PMID 33460649, 2021). "Most of the medulloblastoma-associated mutants in DDX3X/DED1 (ded1-mam) showed substantial growth defects, indicating that functional effects are conserved in yeast." (PMID 33460649, 2021). "The lethality of these ded1-mam mutants suggests an acute loss of DDX3X/Ded1 function for a subset of the medulloblastoma-associated mutations (see Discussion)." (PMID 33460649, 2021). "Overall, these growth phenotypes suggest that the medulloblastoma-associated point mutations are sufficient to alter DDX3X/Ded1 function in yeast, validating the use of S. cerevisiae as a model for understanding the functional consequences of these mutations." (PMID 33460649, 2021). "The results from a wave of medulloblastoma genome-sequencing studies revealed that DDX3X is the second most frequently mutated gene in medulloblastoma (8%, 25/300), followed by CTNNB1 (β-catenin)." (PMID 33627125, 2021). "In this context, DDX3X mutations have also been identified in some cancer types, i.e., medulloblastomas, head and neck squamous cell carcinomas (HNSCC), and hematological malignancies." (PMID 34638314, 2021). "Another genome sequencing analysis of SHH medulloblastoma showed that DDX3X is mutated in 54% of adult SHH medulloblastomas (27/50) and 7.2% of paediatric medulloblastomas (6/83)." (PMID 33627125, 2021). "In order to better understand the biochemical basis of the effects of the medulloblastoma-associated mutations in DDX3X/DED1, we purified His-tagged, recombinant wild-type and mutant Ded1 protein and subjected them to two different in vitro assays." (PMID 33460649, 2021). "Despite the widely shared and well-correlated scanning defect in the ded1-mam mutants, the medulloblastoma-associated mutations in DDX3X/DED1 had variable defects in growth, and many also showed additional functional defects." (PMID 33460649, 2021). "In this study, we have characterized the functional and biochemical effects of medulloblastoma-associated mutations in DDX3X/DED1." (PMID 33460649, 2021). "DDX3X mutations have also been described in medulloblastoma and more detailed functional analyses have shown that these mutations are associated with reduced global mRNA translation." (PMID 32924027, 2020). "Exon sequencing of medulloblastoma patient samples revealed that the occurrence of mutations within DDX3X is significant, suggesting a causative connection." (PMID 29222110, 2018). "DDX3X is implicated in several aspects of RNA biology and mutations in DDX3X are linked to tumorigenesis, especially medulloblastoma." (PMID 30256975, 2018). "Recent genomic studies have reported recurrent DDX3X mutations in numerous tumors including medulloblastoma (MB), but the physiological impact of these mutations is poorly understood." (PMID 27180681, 2016). "DDX3X encodes a DEAD-box family RNA helicase (DDX3) commonly mutated in medulloblastoma, a highly aggressive cerebellar tumor affecting both children and adults." (PMID 27058758, 2016). "Misregulation of DDX3X expression and mutations in the helicase core of DDX3X are associated with tumors, including medulloblastoma, lung- and colorectal cancer and T-cell lymphoma." (PMID 27494274, 2016). "Impairment of translation initiation is also evident in primary medulloblastomas harboring mutations in DDX3X, further highlighting DDX3′s role in this process." (PMID 27058758, 2016). "Medulloblastoma-associated DDX3X mutations occur exclusively the helicase domains and have been shown (or are predicted) to result in catalytically impaired proteins with limited ATPase and helicase activity." (PMID 27058758, 2016). "Recently, whole-exome sequencing identified DDX3X as a target of driver gene mutations that mediate pathogenic β-catenin signaling in medulloblastoma, which supports the CSC theory." (PMID 25343452, 2014).
medulloblastoma (continued). "DDX3X is required for Wnt/β-catenin signaling, and mutated DDX3X has been shown to play a role in pathogenic β-catenin signaling in medulloblastoma." (PMID 25343452, 2014). "Although most studies of DDX3X have focused on its most well-known roles in translation, the medulloblastoma-associated mutations may affect a different function (see non-translational functions of DDX3X above)." (PMID 39062517, 2024). "For improving medulloblastoma treatment, further studying the DDX3X mutations could be immensely helpful in identifying the likely prognosis of the patient and possibly provide more targeted therapy." (PMID 39062517, 2024). "Two other studies have examined growth phenotypes in Saccharomyces cerevisiae, both of which generated mutations in the yeast ortholog DED1 that correspond to the medulloblastoma-associated ones in DDX3X, taking advantage of the high degree of identity between DDX3X and DED1 at these sites." (PMID 39062517, 2024). "Several groups have examined whether the medulloblastoma-associated mutations in DDX3X cause growth defects in model organisms such as yeast." (PMID 39062517, 2024). "Because tumor cells are frequently under stress conditions, and stress responses are often dysregulated in cancer, the role of DDX3X in cellular stress may be impacted by the medulloblastoma-associated mutations." (PMID 39062517, 2024). "Understanding the pathological mechanism of the DDX3X mutations will lead to a better understanding of the course of medulloblastoma and may provide an additional biomarker for diagnosis." (PMID 39062517, 2024). "Given that the primary function of DDX3X is in translation, it has been speculated that the medulloblastoma-associated DDX3X mutations may impair global translation." (PMID 39062517, 2024). "Notably, in medulloblastoma 99.7% (95% CI 99.1–100) of DDX3X missense variants are estimated to be drivers, and all are SGE-depleted (n = 16)." (PMID 38057330, 2023). "WNT medulloblastoma with DDX3X mutation revealed increased gene expression enriched in cell stress and immune response, implicating DDX3X role in inflammasome and innate immune signaling during medulloblastoma development mice models." (PMID 35874614, 2022). "Furthermore, in medulloblastoma, DDX3X mutants led to impairment in mRNA translation, causing the hyper-assembly of stress granules." (PMID 35954483, 2022). "The study revealed that DEAD box helicase DDX3X involved in several pathways of RNA biology could bind to NRAS rG4s and the mutations of DDX3X are associated with tumorigenesis, especially medulloblastoma." (PMID 35625576, 2022). "Additionally, mutations in DDX3X frequently appear in WNT medulloblastoma, which is characterized by alterations of the WNT signalling pathway." (PMID 33627125, 2021). "Determining the role of DDX3X mutations in medulloblastoma is a challenging problem." (PMID 33460649, 2021). "Several studies have examined the effects of the DDX3X mutations identified in medulloblastoma." (PMID 33460649, 2021). "Consistently, further functional studies on mutations in medulloblastoma revealed that DDX3X mutants G302V and G325E have severely defective RNA-stimulated ATPase activity and cannot complement the growth defect in a Ded1p (yeast homologue of DDX3X) temperature-sensitive strain of fission yeast." (PMID 33627125, 2021). "Because DDX3X/Ded1 is well characterized as a translation factor, we first examined whether the medulloblastoma-associated mutations caused defects in translation generally." (PMID 33460649, 2021). "In order to better understand how the medulloblastoma-associated mutations in DDX3X/DED1 contribute to in vivo phenotypes, we tested whether the growth defects of the ded1-mam mutants were dominant or recessive via two different methods." (PMID 33460649, 2021). "We thus hypothesized that the medulloblastoma-associated mutations in DDX3X/DED1 may be specifically affecting this function." (PMID 33460649, 2021).
medulloblastoma (continued). "In fact, in a meta-analysis, DDX3X was the second-most commonly mutated gene in medulloblastoma after the transcription factor β-catenin (CTNNB1), and the mutations were not limited to a particular subtype, although they were especially frequent in Wnt and adult Shh subtypes." (PMID 33460649, 2021). "This knowledge could then be used to help understand what physiological processes are affected by the DDX3X mutations in the development of medulloblastoma and, ultimately, how its effects can be reversed by future therapeutics for the disease." (PMID 33460649, 2021). "These experiments validate DDX3X mutations as drivers of SHH medulloblastoma." (PMID 31204176, 2019). "A previous study indicated that somatic mutations of DDX3X were associated with medulloblastoma." (PMID 26352260, 2015). "Furthermore, whole-exome analyses identified DDX3X as a component of pathogenic β-catenin signaling, in Wnt subgroup medulloblastoma." (PMID 25343452, 2014). "Furthermore, defects in Ded1 activity in yeast may largely recapitulate the molecular effects of DDX3X mutation in medulloblastoma." (PMID 39062517, 2024). "Indeed, the formation of stress granules has been shown to explain the broad suppression of translation observed upon expression of certain medulloblastoma-associated DDX3X mutants, such as G325E, which have reduced enzymatic activity and trigger aberrant stress granule formation in cells." (PMID 36393867, 2022). "Finally, hinting that the translational effects of the DDX3X mutations may be complex, ribosome profiling of cells expressing a medulloblastoma-associated DDX3X mutant showed some mRNA-specific effects, particularly on stress-related genes." (PMID 33460649, 2021). "However, it is important to note that the spectrum of mutations of DDX3X differs between B-cell neoplasms and medulloblastoma (truncating mutations versus nonsynonymous single nucleotide changes) and the functional consequences of DLBCL/CLL-associated DDX3X mutations have not been reported." (PMID 32924027, 2020). "Further research on DDX3X’s mechanism and targets is required to therapeutically target DDX3X and/or its downstream effects in medulloblastoma progression." (PMID 39062517, 2024). "As multiple studies discussed in this review have shown, DDX3X is one of the most commonly recurring mutated genes in medulloblastoma cases, primarily seen in the WNT and SHH-subtypes of medulloblastoma." (PMID 39062517, 2024). "Predominantly missense mutations of DDX3X were identified in our DLBCL samples, which was similar to the mutational spectrum in medulloblastoma." (PMID 38609996, 2024). "Most relevant for its potential functions in medulloblastoma, DDX3X has been reported to play a role in Wnt signaling." (PMID 39062517, 2024). "Tumors in both models were more broadly distributed (to both the cerebellum and brainstem) in Ddx3x knockout lines, suggesting that functional DDX3X restricts the cell lineage origins of medulloblastoma." (PMID 39062517, 2024). "In medulloblastoma cell lines, as for prostate cancer and Ewing sarcoma, the treatment with the DDX3X inhibitor RK-33 reduces cell growth by reducing transcript levels of Wnt-regulated genes." (PMID 35954483, 2022). "Several disease-associated DDX3X mutations are more prone to triggering spontaneous SGs than wild-type DDX3X, and it is thought that this contributes to disease pathophysiology in medulloblastoma and neurodevelopmental delay (DDX3X syndrome)." (PMID 36393867, 2022). "Evidence showed that DDX3X is overexpressed in glioblastoma, medulloblastoma, gallbladder carcinoma, pancreatic ductal adenocarcinoma and chronic myeloid leukemia." (PMID 35954483, 2022). "In mouse models of medulloblastoma, Ddx3x knockout increased disease penetrance and reduced tumor latency, stimulated by inflammasome activation and cell pyroptosis." (PMID 36376979, 2022).